SCUBE2 (signal peptide, CUB domain and EGF like domain containing 2)
Description:
Lipid-binding protein carrier required for sonic hedgehog (SHH) long-range signaling: binds to the dually lipid-modified Sonic hedgehog protein N-product (ShhN) and promotes its release from producing cells, allowing it to act as a morphogen for distant signaling. ShhN is then transferred to the CDON-BOC heterodimer and GAS1 coreceptors to reach its target, the patched receptor (PTCH1 or PTCH2), followed by activation of the smoothened signaling pathway. May also enhance the proteolytic processing (shedding) of the lipid-modified N- and C-terminal of ShhNp at the cell surface. Synergizes with DISP1 to increase SHH secretion. Probable cell surface coreceptor for VEGFR2 involved in VEGFR2-mediated angiogenesis.
Synonyms: CEGP1; Cegf1; Cegb1; FLJ16792; scube/You
Tractability: Antibody: UniProt places it where antibodies can reach, with high confidence; its Gene Ontology location is reachable by antibodies, with high confidence; UniProt predicts a signal peptide or a membrane-spanning region.
Gene: Protein-coding gene on chromosome 11 (9,019,476 to 9,138,114, reverse strand). Ensembl gene ENSG00000175356.
Subcellular location: Secreted; Cell surface
Pathways (Reactome):
Signal Transduction: Release of Hh-Np from the secreting cell
Gene Ontology:
Molecular function: protein binding; protein carrier chaperone; calcium ion binding
Biological process: positive regulation of smoothened signaling pathway; signal transduction
Cellular component: extracellular region; cell surface
Genetic constraint (gnomAD): Loss-of-function variants: 100 observed, 117.93 expected, observed/expected ratio (o/e) 0.85, 90% interval 0.72 to 1. The upper end of that interval is the gene's LOEUF score, 1, which puts it in group 4 of 6, group 1 being the genes least tolerant of losing a copy. Missense variants: 1,132 observed, 1,269.6 expected, observed/expected ratio (o/e) 0.89, 90% interval 0.85 to 0.94. Synonymous variants: 415 observed, 469.93 expected, observed/expected ratio (o/e) 0.88, 90% interval 0.81 to 0.96.
Homologues: Orthologues: chimpanzee SCUBE2 (96% identical), macaque SCUBE2 (93% identical), dog SCUBE2 (92% identical), rabbit SCUBE2 (89% identical), guinea pig SCUBE2 (87% identical), rat Scube2 (85% identical), mouse Scube2 (84% identical), tropical clawed frog scube2 (71% identical), zebrafish scube2 (66% identical). Paralogues in human: SCUBE1 (63% identical), SCUBE3 (59% identical).
Diseases named in the same sentence as SCUBE2 in open-access papers:
SCUBE2 is named in the same sentence as 33 diseases in open-access papers, as found by Europe PMC text mining. Sharing a sentence is not in itself a finding about the gene and the disease. The quoted sentences say what the papers report.
breast carcinoma (34 papers, 2010 to 2026). "A recent study found that the specific expression of SCUBE2 in luminal-type breast cancer is associated with shortened bone metastasis-free survival." (PMID 38041134, 2023). "Meanwhile, human SCUBE2 has been implicated in breast cancer biology." (PMID 37237303, 2023). "Interestingly, SCUBE2 has been associated with ER/PR positive tumors 35 and proposed as a tumor suppressor in breast cancer, yet it has also been shown as the only common gene in outcome‐predictive signature assays in breast cancer." (PMID 34189853, 2021). "For example, Ki-67, STK15, Survivin, Cyclin B1, and MYBL2 have all been associated with breast cancer proliferation; Stromelysin 3 and Cathepsin L2 have been associated with invasion; and ER, PR, Bcl2, and SCUBE2 have been associated with responsiveness to Estrogen." (PMID 29848291, 2018). "DTL, ECT2, MTDH, PRC1 and RFC4 have all been previously implicated in breast cancer; SCUBE2 and STK32B deletions have been found to be related to mental deficits in humans; and ZNF533 has been found to be associated with the Hedgehog signaling pathway in Zebrafish." (PMID 20584321, 2010). "Further studies have shown that SCUBE2 can mediate the bone metastasis of tubular breast cancer by regulating the immunosuppressive osteoblast niche." (PMID 39294728, 2024). "Breast cancer cell proliferation and tumor growth were found to be significantly influenced by changes in SCUBE2 protein levels." (PMID 37237303, 2023). "HOXB gene family, FOXA1, SLC39A11, and SCUBE2 were found to play well-established roles in breast cancer development, and thus were the focus on our further analysis." (PMID 37293596, 2023). "Another implication is that four of the genes identified in this study—AGR2, AGR3, TFF3, and SCUBE2—have protein products that are secreted in the blood by breast cancer." (PMID 36836779, 2023). "Research on SCUBE2 has been largely driven by findings from zebrafish genetic studies and human breast cancer genomic studies." (PMID 37237303, 2023). "Since the roles of SCUBE2 in breast cancer appear to be complex and context-dependent, further investigations are needed on this topic." (PMID 37237303, 2023). "Analogously, upregulated SCUBE2 in breast cancer primary tumor cells can be proteolytically cleaved by matrix metalloproteinase 2 (MMP-2) to separate the C-terminal CR and CUB domains from the N-terminal EGF-like repeats and the spacer region." (PMID 37237303, 2023). "Mechanically, regulated by ER signaling in luminal-type breast cancer, SCUBE2 acts in an autocrine manner on cancer cells, leading to Hedgehog signal activation, osteoblast differentiation, and immune suppression-mediated bone metastasis." (PMID 38041134, 2023). "Most importantly, SCUBE2 is expressed in breast cancer stem cells and plays a role in the metastasis of triple-negative breast cancer." (PMID 37237303, 2023). "Four drug resistance genes (AMIGO2, LGALS3BP, SCUBE2 and WLS) were found to be promising tools for ER+ and HER2- breast cancer risk stratification." (PMID 34760348, 2021). "Overexpression of SCUBE2 reversed epithelial mesenchymal transition (EMT) and associated cellular signaling in breast cancer." (PMID 32183060, 2020). "Mounting evidence suggests that SCUBE2 acts as a tumor suppressor in breast cancer, non small cell lung cancer (NSCLC), colorectal cancer and gastric cancer." (PMID 32196521, 2020). "Signal peptide-CUB-EGF domain-containing protein 2 (SCUBE2) is a breast cancer tumor suppressor gene that is silenced due to promoter methylation." (PMID 32183060, 2020). "Initially, we found that SCUBE2 showed a significant lower expression in breast cancer tissues than in the adjacent normal ones." (PMID 31404982, 2019). "A previous study reported that SCUBE2 inhibited the migration and invasion of breast cancer cells by EMT reversal." (PMID 31404982, 2019).
breast carcinoma (continued). "In the present study, we identified for the first time that EGCG treatment reactivated the SCUBE2 expression by reducing the methylation status, finally leading to the inhibition of breast cancer progression." (PMID 31404982, 2019). "In this study, we found that the SCUBE2 promoter in breast cancer tissues was significantly higher methylated in comparison to the adjacent control (p < 0.01)." (PMID 31404982, 2019). "A previous study reported that the expression of signal peptide-CUB (complement protein C1r/C1s, Uegf, and Bmp1)-EGF (epidermal growth factor) domain-containing protein 2 (SCUBE2) gene was significantly inhibited in breast cancer cells." (PMID 31404982, 2019). "Silencing SCUBE2 triggered the acceleration of the E-cadherin and the decrease of the vimentin in breast cancer cells." (PMID 31404982, 2019). "Among the other genes in the list, NAT1, DNALI1, SCUBE2, and TFF1 have been implicated in breast cancer." (PMID 23365541, 2012). "SCUBE2 is a secretory protein directly regulated by estrogen receptor alpha (ERα), as demonstrated by chromatin immunoprecipitation (ChIP) and reporter assays in ER+ breast cancer cells." (PMID 41596432, 2026). "SCUBE2, B4GALT1 and MYO3B genes also exemplify the relationship between decitabine-induced gain of multiple ER-bound enhancer–promoter interactions and activation of their ER target genes that are associated with good prognosis in ER+ breast cancer." (PMID 38182927, 2024). "SCUBE2 also emerged as a key predictor of chemoresistance in breast cancer in our recent study." (PMID 37700842, 2023). "Moreover, SCUBE2 expression and function in different types of breast cancer appear to be dynamically regulated at various stages of disease progression." (PMID 37237303, 2023). "The findings from our breast cancer studies might therefore partly explain why the zebrafish Scube2 can attenuate Bmp in a permissive manner." (PMID 37237303, 2023). "The authors found that treatment with EGCG reverses DNA methylation of SCUBE2 in breast cancer." (PMID 37237303, 2023). "In addition, SCUBE2 expression is upregulated in breast cancer stem cells, promotes EMT, and enhances metastasis of triple-negative breast cancer by promoting NOTCH signaling." (PMID 37237303, 2023). "In addition, the study showed that EGCG inhibits breast cancer cell viability and suppresses the migration and invasion capacities of the cells, while knockdown of endogenous SCUBE2 blocks these inhibitory effects of EGCG in breast cancer cells." (PMID 37237303, 2023). "We speculated that the downregulation of SCUBE2 in concert with FOXA1 is part of the EMT program that plays important roles in modulating breast-cancer cell migration and invasion." (PMID 37293596, 2023). "A recent study demonstrated that the tumor-secreted factor signal peptide, cubulin domain, epidermal-growth-factor-like protein 2 (SCUBE2), regulated by the ER signaling pathway, mediates bone metastasis in luminal-type breast cancer through immune suppression." (PMID 38041134, 2023). "SCUBE2 is downregulated in invasive BrCa but overexpressed by breast cancer stem cells (BCSCs)." (PMID 34007962, 2021). "This resulted in higher expression levels of SCUBE2 and reduced breast cancer progression." (PMID 32183060, 2020). "Furthermore, SCUBE2 expression is part of the 70-gene signature (MammaPrintTM) to deliver prognostic information in breast cancer patients." (PMID 32196521, 2020). "However, when breast cancer cells were treated with EGCG, the loss of SCUBE2 expression status was reversed, causing higher SCUBE2 levels compared to untreated cells." (PMID 31404982, 2019). "We next determined whether SCUBE2 silence can block the regulation of EGCG in the invasive behavior of breast cancer cells." (PMID 31404982, 2019).
breast carcinoma (continued). "SCUBE2, coding a secreted and cell-surface glycoprotein with multiple domains, has been reported to be a novel tumor suppressor gene in various human cancers including colorectal, endometrial, and breast cancer." (PMID 31404982, 2019). "Consistently, a significantly marked decrease of total DNMTs activity was detected in MCF-7 and MDA-MB-231 cells treated with EGCG or 5-aza-dC (p < 0.01), which suggested that EGCG can reactivate the SCUBE2 gene in human breast cancer cells by reducing DNMT activity and DNA methylation." (PMID 31404982, 2019). "Therefore, we hypothesized that EGCG may play important roles in regulating the methylation and expression of the tumor suppressor gene SCUBE2 and further suppress migration and invasion of breast cancer cells." (PMID 31404982, 2019). "The PGR (progesterone receptor), BCL2 Apoptosis Regulator and SCUBE2 (Signal Peptide, CUB Domain And EGF Like Domain Containing 2) are known to be a favorable prognostic marker on breast cancer recurrence." (PMID 34462515, 2021). "In this study, we investigated the phenotypic effect of tea catechins on human breast cancer cells and clarified the epigenetic mechanism of how EGCG regulated the DNA methylation of the SCUBE2 gene." (PMID 31404982, 2019). "In conclusion, this study for the first time reported that EGCG can reverse the DNA methylation status and reactivate the expression of the SCUBE2 gene by reducing DNMT expression and activity in human breast cancer cells, MCF-7 and MDA-MB-231." (PMID 31404982, 2019). "For protein-coding genes, SCUBE2 and SDPR were highly expressed in the luminal A subtype, LAPTM5 and YWHAH in the HER2 subtype, and S100A11 and C6ORF211 in the luminal B subtype of breast cancer." (PMID 31801944, 2019). "In summary, this study reported for the first time that SCUBE2 methylation can be reversed by EGCG treatment, finally resulting in the inhibition of breast cancer progression." (PMID 31404982, 2019). "Furthermore, SCUBE2 expression contributes to Notch pathway activation and EMT in breast cancer stem-like cells, increasing their invasiveness and bone-tropic capacity." (PMID 41596432, 2026). "Moreover, SCUBE2, TMEM26, and SMOC2 were validated as subtype-specific coding genes in luminal A breast cancer, CDK12 and SDC1 in HER2 breast cancer and PSAT1 in triple negative breast cancer in TCGA and GEO datasets." (PMID 31801944, 2019). "The expression of SCUBE2 predicts a favorable outcome in epidermal growth factor receptor (EGFR)-negative and estrogen receptor (ER)α-positive breast cancers." (PMID 37237303, 2023).
breast tumor (5 papers, 2019 to 2023). "SCUBE2 was reported to work synergistically with FOXA1 as a novel breast-tumor suppressor, driving the reversal of epithelial–mesenchymal transition (EMT)." (PMID 37293596, 2023). "SCUBE2 functions as a novel breast tumor suppressor and possesses an oncogenic role in breast-cancer stem cells." (PMID 36142489, 2022). "Further detection revealed that the SCUBE2 gene promoter region was hypermethylated in the histologic breast tumor." (PMID 31404982, 2019). "We found that signal peptide-CUB (complement protein C1r/C1s, Uegf, and Bmp1)-EGF (epidermal growth factor) domain-containing protein 2 (SCUBE2), a tumor suppressor gene, was hypermethylated in breast tumors." (PMID 31404982, 2019). "In the preliminary experiment of this study, we found that the promoter region of SCUBE2 was hypermethylated in breast tumor." (PMID 31404982, 2019). "Furthermore, SCUBE2 functions as a tumor suppressor gene and is hypermethylated in breast tumors." (PMID 36142489, 2022).
atherosclerosis (3 papers, 2022 to 2024). A disease characterized by the build-up of fatty material and calcium deposition in the arterial wall resulting in partial or complete occlusion of the arterial lumen. "SCUBE2 is involved in vascular endothelial function changes and vascular complications, particularly in diabetes and atherosclerosis." (PMID 36082132, 2022). "Notably, SCUBE2 encodes a protein which interacts with vascular endothelial growth factor (VEGF) receptor 2 to regulate VEGF-induced angiogenesis, thus providing biologic plausibility for this gene in atherosclerosis." (PMID 35020748, 2022).
colorectal cancer (3 papers, 2019 to 2023). A primary or metastatic malignant neoplasm that affects the colon or rectum. "For instance, SCUBE2 is commonly downregulated in non-small-cell lung cancer (NSCLC), glioma tissues, colorectal cancer tissues, parathyroid adenoma tissues, gastric carcinoma tissues, and invasive regions of bladder cancer." (PMID 37237303, 2023). "Meanwhile, overexpression of SCUBE2 inhibits the proliferation of NSCLC, glioma, and colorectal cancer cells, and it also suppresses cell migration and invasion." (PMID 37237303, 2023).
gastric cancer (3 papers, 2020 to 2022). A primary or metastatic malignant neoplasm involving the stomach. "Moreover, the poor prognosis of gastric cancer patients was associated with SCUBE2 downregulation." (PMID 33336052, 2020). "In gastric cancer, lower SCUBE2 expression exhibited significantly poor relapse-free survival and overall survival in patients." (PMID 36142489, 2022).
rheumatoid arthritis (3 papers, 2020 to 2024). A chronic, systemic autoimmune disorder characterized by inflammation in the synovial membranes and articular surfaces. "Downregulation of PVT1 reduces proliferation and IL-1β release while inducing apoptosis of rheumatoid arthritis fibroblast-like synoviocytes (RA-FLS) by mediating the miR-543/SCUBE2 axis." (PMID 39062113, 2024). "In another study, synovial tissue of rheumatoid arthritis rats showed a high level of SCUBE2 and low level of miR-543, which can target SCUBE2 and interact with a long non-coding RNA called plasmacytoma variant translocation." (PMID 37237303, 2023).
bladder cancer (2 papers, 2013 to 2020). "Downregulated gene products include putative tumor suppressor genes (SCUBE2), factors previously reported as lost in aggressive bladder cancer (FOXA1, GATA3, UPK3A), and metabolizing enzymes with polymorphisms affecting cancer risk (UGT1A10, UGT1A7)." (PMID 24134934, 2013). "Therefore, the exact role of SCUBE2 in bladder cancer, as regards Shh signalling, requires further investigation." (PMID 32374509, 2020).
diabetes (2 papers, 2022 to 2025). "Additionally, SCUBE-2 has been suggested to play a role in endothelial dysfunction and reactive oxygen species (ROS) accumulation in conditions such as diabetes, hyperglycemia, and dyslipidemia, all of which are associated with increased vascular complications." (PMID 40498954, 2025).
fibrosis (2 papers, 2025). the formation of excess fibrous connective tissue in an organ or tissue in a reparative or reactive process. "Using lineage tracing in preclinical fibrosis models, the authors showed that naive Scube2+ alveolar fibroblasts underwent a profibrotic phenotypic switch prior to proliferating within areas of fibrotic remodeling." (PMID 41243968, 2025).
glioma (2 papers, 2023). A benign or malignant brain and spinal cord tumor that arises from glial cells (astrocytes, oligodendrocytes, ependymal cells). "SCUBE2 participates in SHH signaling and, when overexpressed, decreases glioma cell proliferation, migration, and invasion." (PMID 37628788, 2023).
hepatocellular carcinoma (2 papers, 2022 to 2025). A malignant tumor that arises from hepatocytes. "Lower transcriptional and protein expression due to the hypermethylation of SCUBE2 has been reported in hepatocellular carcinoma patients." (PMID 36142489, 2022).
triple-negative breast carcinoma (2 papers, 2019 to 2023). An invasive breast carcinoma which is negative for expression of estrogen receptor (ER), progesterone receptor (PR), and human epidermal growth factor receptor 2 (HER2). "Furthermore, low expression of SCUBE2 is associated with reduced time to disease-related mortality and contributes to tumorigenesis in triple-negative breast cancer." (PMID 37237303, 2023).
adenoma (1 paper, 2016). A neoplasm arising from the epithelium. "Truncating mutations were also validated in SCUBE2, RELN, FBXW7, MLL3, WTX/FAM123B, OTUD7B and KPRP across the MAP and FAP adenomas." (PMID 26414517, 2016).
arteriosclerosis (1 paper, 2023). A vascular disorder characterized by thickening and hardening of the walls of the arteries. "Despite the lack of detailed studies exploring the molecular mechanism of SCUBE2 in arteriosclerosis, it has been suggested that SCUBE2 may play an important role in the development of atherosclerotic plaques." (PMID 37237303, 2023).
autoimmune disease (1 paper, 2023). A disorder resulting from loss of function or tissue destruction of an organ or multiple organs, arising from humoral or cellular immune responses of the individual to their own tissue constituents. "Although the genome-wide association study provided evidence that SCUBE2 is a genetic determinant of plasma β2-glycoprotein I level, further investigations will be required to elucidate the putative role of SCUBE2 in β2-glycoprotein I-associated cardiovascular and autoimmune diseases." (PMID 37237303, 2023).
colon-cancer (1 paper, 2022). "Kaplan–Meier data and univariate analysis demonstrated that colon-cancer patients with SCUBE2-positive tumors had better overall survival and disease-free survival in comparison to patients with SCUBE2-negative tumors." (PMID 36142489, 2022).